ENSG00000288725 (novel protein)
Gene: Protein-coding gene on chromosome 16 (56,430,556 to 56,501,497, reverse strand). Ensembl gene ENSG00000288725.
Genetic constraint (gnomAD): Missense variants: 388 observed, 474.05 expected, observed/expected ratio (o/e) 0.82, 90% interval 0.75 to 0.89. Synonymous variants: 152 observed, 170.55 expected, observed/expected ratio (o/e) 0.89, 90% interval 0.78 to 1.02.